MTOR (mechanistic target of rapamycin kinase)
Diseases named in the same sentence as MTOR in open-access papers (continued):
Sharing a sentence is not in itself a finding about the gene and the disease.
gynecological cancers (22 papers, 2014 to 2025). "In accordance with our results, AKT downregulation has already reported as being involved in autophagy and apoptosis through the beclin-1 block, and the PI3K/AKT/mTOR pathway has been implicated as one of the principals of autophagy pathways in gynecological cancers." (PMID 31683835, 2019). "Given the pathway’s importance in cancer biology and potential as a therapeutic target, further research into PI3K/AKT/mTOR inhibitors is warranted to improve the outcomes of gynecological cancers." (PMID 40647429, 2025). "The frequent activation of the PI3K/AKT/mTOR (PAM) pathway makes it an attractive therapeutic target in gynecological cancers." (PMID 39456616, 2024). "Background/Objectives: The PI3K/AKT/mTOR (PAM) pathway is frequently activated in gynecological cancers." (PMID 39456616, 2024). "Overactivation of the PI3K-Akt-mTOR pathway has been found in human cancer progression, particularly in gynecological cancers." (PMID 38275362, 2023). "Since activation of AKT is shown to be related to PARPi resistance in recent studies, there are some ongoing trials trying to combine PI3K/AKT/mTOR inhibitors and PARPi in gynecologic cancers." (PMID 34680987, 2021). "Monotherapy with PI3K/AKT/mTOR inhibitors in gynecologic cancers, however, has been shown to have a limited clinical benefit, and no drug is approved by the US FDA in gynecologic cancer currently." (PMID 34680987, 2021). "A group of effectors triggering gynecological cancer development through the mTOR pathway can be identified as growth factors." (PMID 31947591, 2020). "Studies of the mechanistic (mammalian) target of rapamycin inhibitors (mTOR) represent a step towards the targeted treatment of gynecological cancers." (PMID 31947591, 2020). "The current level of knowledge is that the outcomes for women with gynecological cancer and elevated levels of mTOR signaling pathway targets seem to be significantly worse than those for women with normal mTOR levels." (PMID 31947591, 2020). "The downstream effects in gynecological cancer show an important interconnection of mTOR with YB-1 activity." (PMID 31947591, 2020). "Yet, due to upregulation of the Pi3k/Akt/mTor signaling pathway in endometrial hyperplasia and gynecological cancer, the samples with these pathological changes were removed from further genetic and histochemical analysis." (PMID 31955151, 2020). "The present study reviewed the available evidence regarding the potential impact of some mTOR pathway inhibitors in the treatment of gynecological cancer." (PMID 28286604, 2017). "It should be noted that mTOR lies downstream of the PI3K-AKT signaling cascade, a pathway frequently mutated in gynecological cancers and of paramount importance in the control of cell fate." (PMID 28008141, 2017). "It is shown that the activation of the PI3K/AKT/mTOR pathway is related to poor outcome, and it is particularly relevant in gastrointestinal and gynecological cancers." (PMID 24777052, 2014). "Research into the mechanism of endocrine responsiveness and resistance in breast and gynecologic cancers has revealed that the PI3K/AKT/mTOR pathway becomes activated and utilized by cancer cells to bypass the effects of hormone therapy." (PMID 24912489, 2014). "Previous reports suggested that PIK3CA mutations might predict sensitivity to treatment with PI3K/AKT/mTOR inhibitors, such as everolimus, in multiple tumor types including gynecologic cancer." (PMID 33207545, 2020). "This led to the development and clinical testing of mTOR inhibitors in gynecological cancers." (PMID 31947591, 2020). "Yet, targeting mTOR alone has led to unsatisfactory outcomes in gynecological cancer." (PMID 31947591, 2020).
gynecological cancers (continued). "This combination is of particular interest for patients with KRAS mutations considering this mutation is often associated with an absence of response when using PI3K/AKT/mTOR inhibitor alone in gynecological cancers." (PMID 28008141, 2017). "PI3K/AKT/mTOR pathway alterations are common in breast and gynecologic cancers." (PMID 24912489, 2014). "This suggests that, to achieve effective growth-inhibitory effects in gynecologic cancer cells, a PAM inhibitor should be able to target with equal, low nanomolar, potency both PI3K and mTOR." (PMID 39456616, 2024). "According to our results, all three gynecologic cancer types (both Chinese and TCGA) share a dMMR-signature, four recurrent CNV events, as well as the extensive alterations in PI3K-Akt-mTOR signaling and cilium component genes." (PMID 33194730, 2020). "Encouraging results from in vitro studies and early stage clinical trials of first generation mTOR and PI3K inhibitors in gynecological cancers have recently become available." (PMID 24526917, 2014). "Gedatolisib, a well-tolerated panPI3K/mTOR inhibitor targeting all Class I PI3K isoforms, mTORC1 and mTORC2, could represent an effective treatment option for patients with gynecologic cancers." (PMID 39456616, 2024). "Alternatively, screening for PIK3CA mutations with targeted use of mTOR inhibitors may be another useful strategy since patients with these mutations may be more responsive to PI3K/AKT/mTOR inhibitors than patients without these mutations in gynecologic cancers." (PMID 26959121, 2016).
pneumonia (22 papers, 2013 to 2026). An acute, acute and chronic, or chronic inflammation focally or diffusely affecting the lung parenchyma, caused by an infection in one or both of the lungs (by bacteria, viruses, fungi, or mycoplasma.). "Mechanistically, bitter taste pathway disruption dysregulated the mTOR pathway, reduced eNOS expression, and delayed resolution of pneumonia-induced injury." (PMID 41142782, 2025). "Actually, some PI3K/Akt/mTOR inhibitors have been reported to often induce severe ADRs such as cardiac toxicity, liver toxicity, immunosuppression, and pneumonia." (PMID 38700923, 2024). "Alternatively, systemic treatment with drugs targeting PI3K downstream effectors was attempted but the mTOR inhibitor everolimus was found to cause serious adverse events, including noninfectious pneumonia, and to reduce overall survival in IPF35." (PMID 30542075, 2018). "Clinically, mTOR inhibitors such as rapamycin are used as immunosuppressants after solid organ and stem cell transplantation, and the systemic administration of mTOR inhibitors in the context of pneumonia or other infections that lead to ARDS may be detrimental." (PMID 34138757, 2021). "There were a total of ten pneumonia-related pathways, which were TNF signaling, MAPK signaling pathway, chemokine signaling, NF-κB signaling, mTOR signaling, VEGF signaling, autophagy-animal, Toll-like receptor signaling, FoxO signaling, and NOD-like receptor signaling." (PMID 38671867, 2024). "In addition, the findings of the present investigation determined that in the pneumonia model of animals, the level of mTOR in lung tissue was significantly increased, while a considerable decrease in the levels of LC3 and BECN1 was induced after pneumonia." (PMID 38580929, 2024). "Among respiratory tract infections, no increase in the risk of specific types of pneumonia such as PcP, invasive mold or CMV infection was found to be associated with mTOR inhibition." (PMID 30700842, 2019).
serous ovarian cancer (22 papers, 2015 to 2024). "STK11 loss has already been shown in ovarian serous carcinoma and may favor mTOR activation." (PMID 35965534, 2022). "A reverse phase protein analysis study in high grade serous ovarian cancer (HGSOC) identified anti-apoptotic proteins as a mechanism of resistance to inhibitors of the PI3K/Akt/mTOR pathway." (PMID 39739112, 2024). "Although there is no clear evidence of the crosstalk between miR-130a and the mTOR pathway during DR, it is noteworthy that miR-130a is a negative regulator of TSC1, capable of upregulating the mTOR pathway in high-grade serous ovarian carcinoma." (PMID 36388931, 2022). "Particularly, the PI3K‐AKT and mTOR signalling pathways (red), frequently altered in high grade serous ovarian carcinoma showed significant enrichment in EV extracts." (PMID 34429857, 2021). "A growing number of studies have proved the activation of the PI3K/AKT/mTOR pathway in EOC, although the Cancer Genome Atlas research detected a low mutational rate (< 5%) of PI3KCA, AKT and PTEN in high-grade serous ovarian carcinomas (HsOCs)." (PMID 29685168, 2018). "Specific attention is with the mTOR pathway, found to be activated in about half of the high grade serous ovarian cancer patients." (PMID 27090655, 2016). "Recently, a therapeutic strategy targeting the mTOR-HIF-1α-VEGF pathway in OCCC has been proposed based on the finding that p-mTOR expression is more prominent in OCCC than ovarian serous carcinoma." (PMID 26497956, 2015). "The PI3K/AKT/mTOR pathway is unregulated in approximately 70% of OC patients while activated MAPK pathway was more frequently expressed in low-grade (81%) as compared with high-grade ovarian serous carcinomas (41%)." (PMID 35372029, 2022). "Finally, further investigation in high grade serous ovarian cancer is needed as an extension of this study to confirm the crosslink of PI3K/Akt/mTOR signaling with EMT and CSC." (PMID 31234823, 2019). "We therefore analyzed if this effect could imply the canonical PI3K/AKT/mTOR pathway that is the most frequently deregulated pathway in high grade serous ovarian cancer." (PMID 25627260, 2015). "Aberrant activation of the RAS/MAPK pathway is reported in 25% of high-grade serous ovarian cancer (HGSOC) which accounts for 70% of EOCs and PI3K/AKT/mTOR signaling is increased in ~40–50% of EOC73." (PMID 35791346, 2022). "A recent study has shown the differential sensitivity of low-grade serous ovarian carcinoma cells and HGSOC cells to mTOR inhibitors." (PMID 34944743, 2021). "PI3KCA, specifically, have been shown to be amplified and overexpressed in cases of high grade serous ovarian cancer, while AKT and mTOR activation have been observed frequently in clear cell ovarian carcinoma." (PMID 33659215, 2020). "Our study is the first to investigate the novel AKT/mTOR dual inhibitor, SPR965, in the setting of serous ovarian cancer." (PMID 33659215, 2020). "We also performed IHC for phospho-mTOR and phospho-AKT, another key downstream marker of PI3K activation, on slides of high-grade serous ovarian cancer tissue and scored them using the same system as for AR IHC." (PMID 34926721, 2019). "A very recent study in high grade serous ovarian carcinoma documented the correlation of VEGFA levels and poor prognosis, rendering VEGFA an ideal candidate to stratify patients prone to drug resistance upon mTOR pathway upregulation." (PMID 27090655, 2016). "Increased AKT activation has been noted observed in high-grade and late-stage serous ovarian cancer, in which AKT exerts anti-apoptotic effects, antagonizes cell cycle arrest, modulates angiogenesis, and activates mRNA translation via mTOR signaling." (PMID 26267321, 2015). "Combining with a PI3K/mTOR pathway inhibitor mitigated the CHK1 inhibitor-induced RAD51-mediated HR repair and augmented replication stress, leading to cell death in high-grade serous ovarian carcinoma." (PMID 35860572, 2022).
serous ovarian cancer (continued). "Stratifying drug resistant high grade serous ovarian cancer via VEGFA, and specifically treating with mTOR inhibitors in case of activation of the pathway may allow adding precision for overcoming resistance to first line therapy." (PMID 27090655, 2016).
T-cell lymphoma (22 papers, 2010 to 2025). "Everolimus, an mTOR inhibitor, has demonstrated antiproliferative and antiangiogenic effects in solid tumours and immunosuppressive properties, providing affective in T-cell lymphoma (TCL) with a 44% response rate in relapsed patients." (PMID 40334012, 2025). "The demonstrated absence of PTEN protein in the majority of these T-LBLs and the concomitant activation of AKT in all these T cell lymphomas raised the possibility that these T cell tumors require PI3K/AKT/mTOR signaling for their survival." (PMID 39637056, 2024). "The phosphatidylinositol 3-kinase inhibitor LY294002 was used to inhibit Akt to verify miR-150 increase NK/T cell lymphoma cell radiorsensitivity through suppress the PI3K/AKT/mTOR pathway." (PMID 29386059, 2018). "Everolimus, which targets the mammalian target of rapamycin (mTOR) pathway, appears to be effective in treating T cell lymphoma by inhibiting malignant T cell proliferation." (PMID 27540476, 2016). "The mammalian target of rapamycin (mTOR), in response to nutritional and environmental cues, regulates a number of growth and survival pathways in cancer, including T-cell NHL, and negatively regulates autophagy." (PMID 28031823, 2016). "Mechanistically, mTOR inhibition not only restricts tumor growth but also enhances T cell activation to augment tumor specific immunity, underscoring the therapeutic potential of mTOR inhibitor in T cell lymphomas." (PMID 41394820, 2025). "Responses following mTOR inhibition have been observed in patients with relapsed/refractory T-cell NHL, and by promoting autophagy and ICD may be rationally combined with both HDAC inhibitors and CPB." (PMID 28031823, 2016). "Computational analysis identified key T-cell lymphoma targets, with molecular docking suggesting DMBP’s anticancer properties through interactions with proteins like AKT1 and mTOR." (PMID 40699833, 2025). "Here, we evaluated and compared the effects of the pan-PI3K inhibitor BKM120 and the dual PI3K/mTOR inhibitor BEZ235 on mantle, follicular, and T-cell lymphomas." (PMID 26557706, 2015). "Here, we have evaluated and compared the effects of the pan-PI3K inhibitor BKM120 and the dual PI3K/mTOR inhibitor BEZ235 on mantle, follicular, and T-cell lymphomas." (PMID 26557706, 2015).
gastrointestinal stromal tumor (21 papers, 2010 to 2025). "NPTX1 and NPTX2 were reported to cause dysfunction of the PI3K/AKT/mTOR pathway thereby affecting tumor progression in glioma, gastrointestinal stromal tumors (GIST) and subependymal giant cell astrocytoma." (PMID 33013829, 2020). "A more recent study revealed that blocking the PD-1/PD-L1 pathway reduced the apoptosis of CD8+ T cells cocultured with a gastrointestinal stromal tumor via the activation of the PI3K/Akt/mTOR signaling pathway." (PMID 38791040, 2024). "Activation of the phosphoinositide 3-kinase (PI3K)/Akt/mTOR pathway is frequently detected in human malignancies, including gastrointestinal stromal tumors (GIST) and soft tissue sarcomas (STS)." (PMID 33266502, 2020). "Furthermore, blocking the PD-1/PD-L1 pathway in gastrointestinal stromal tumors can reduce the apoptosis of CD8+ T cells by governing the PI3K/AKT/mTOR pathway." (PMID 35682571, 2022). "It has been found that the PD-1/PD-L1 blockade in gastrointestinal stromal tumors (GIST) attenuate apoptosis of CD8+ T cells via regulation of PI3K/AKT/mTOR pathway." (PMID 34439774, 2021). "The oncogene c-Kit drives IDO expression in gastrointestinal stromal tumors (GIST) via the mammalian target of rapamycin (mTOR) and the transcription factor ETV4." (PMID 24657910, 2014). "Patients treated with imatinib for gastrointestinal stromal tumor (GIST) with c-KIT mutations in exon 11 have an 83.5% response rate versus 47.8% in patients with exon 9 mutations, and PIK3CA H1047R mutations may be more sensitive to PI3K/Akt/mTor inhibitors than other PIK3CA mutations." (PMID 26418953, 2015).
Hypercholesterolemia (21 papers, 2010 to 2024). An increased concentration of cholesterol in the blood. "The use of mTOR inhibitors was also found to be associated with the development of significant hypercholesterolemia in agreement with previous studies." (PMID 33441656, 2021). "Postoperative complication of biliary stricture after LDLT and the use of mTOR inhibitor were independently associated with development of significant hypercholesterolemia after LDLT (odds ratio [OR] 2.09, 95% CI 1.39–3.13; p < 0.0001 and OR 1.97, 95% CI 1.13–3.41; p = 0.02, respectively)." (PMID 33441656, 2021). "In human patients treated with rapamycin and its derivative mTOR inhibitor, everolimus, moderate hypertriglyceridemia and mild to moderate hypercholesterolemia are relatively common while severe hypertriglyceridemia is rare." (PMID 38094495, 2023). "Hypercholesterolemia also induces hyperactive mammalian target of rapamycin (mTOR) signaling in the heart, whereby protein synthesis and cell growth are promoted by the mTOR complex 1 (mTORC1)." (PMID 35884897, 2022). "Hypercholesterolemia is a frequent side effect of mTOR inhibition in TSC patients, and predominantly occurs within the first year of treatment." (PMID 35804402, 2022). "In effect, mTOR inhibitors worsen cyclosporine-induced hypercholesterolaemia and steroid-induced hypertriglyceridaemia." (PMID 36009482, 2022). "In summary, hypercholesterolemia is a frequent adverse effect of mTOR inhibition in TSC patients, which occurs mainly in the first year of treatment." (PMID 35804402, 2022). "Of note, the use of mechanistic target of rapamycin (mTOR) inhibitors was more frequent in the hypercholesterolemia group (9.7% vs. 17.7%; p < 0.02)." (PMID 33441656, 2021). "Accordingly, the aims of the present study were to investigate the status of autophagy and mTOR pathways in isolated hypercholesterolemia and to examine apoptosis and necroptosis in a hypercholesterolemic rat model." (PMID 28330474, 2017). "In this study we showed first that isolated hypercholesterolemia downregulates cardiac autophagy and activates mTOR pathway." (PMID 28330474, 2017). "Another limitation is that the effect of hypercholesterolemia on autophagy, apoptosis, necroptosis and mTOR signaling pathways was assessed only in the left ventricular myocardium." (PMID 28330474, 2017). "Here we have shown that hypercholesterolemia induces the attenuation of cardiac autophagy in parallel with the activation of mTOR pathway and an elevation of apoptosis." (PMID 28330474, 2017). "Though mouth ulcers, skin rashes, hypercholesterolemia, and hematological disturbances are common with mTOR inhibitor use, they are generally manageable." (PMID 24719752, 2014). "Hypercholesterolemia or hypertriglyceridemia have been reported with the mTOR inhibitors, and one group of investigators recommends treating this adverse event with statins in patients continuing on long-term temsirolimus treatment." (PMID 21092307, 2010). "Our data show that isolated hypercholesterolemia suppresses basal cardiac autophagy and that the decrease in autophagy may be a result of an activated mTOR pathway." (PMID 28330474, 2017). "In order to investigate whether hypercholesterolemia affects mTOR pathway we measured the phosphorylation of mTOR and ribosomal S6 proteins." (PMID 28330474, 2017). "In addition, isolated hypercholesterolemia in rats suppressed basal cardiac autophagy and this decrease may have been the result of an activated mTOR pathway." (PMID 31484164, 2019). "However, it is unknown whether isolated hypercholesterolemia disturbs autophagy or the mammalian target of rapamycin (mTOR) pathways." (PMID 28330474, 2017).